PCAT6 (prostate cancer associated transcript 6)
Diseases named in the same sentence as PCAT6 in open-access papers (continued):
Sharing a sentence is not in itself a finding about the gene and the disease.
cancer (continued). "Emerging evidence has shown that PCAT6 expression is upregulated in various cancers and plays oncogenic roles in cancer development." (PMID 33634115, 2021). "In comparison with normal tissue, PCAT6 expression was increased in all included cancer tissues, and the observed differences were statistically significant (P < 0.05)." (PMID 34247605, 2021). "Here, we review the regulatory mechanisms of PCAT6 in different cancers, and in-depth study is expected to provide new therapeutic targets for these diseases." (PMID 34327141, 2021). "In the present study, we first explored the role of PCAT6 in tumors and found a significant correlation between PCAT6 overexpression and cancer metastasis." (PMID 34247605, 2021). "In this review, we focus on the latest studies involving PCAT6 in the diagnosis, treatment, and prognosis of malignant tumors of the digestive, respiratory, urinary, reproductive, motion, and nervous systems." (PMID 34327141, 2021). "PCAT6 expression was significantly up-regulated in four types of cancer, which was validated using the GEPIA cohort." (PMID 34247605, 2021). "PCAT6 can promote the development and progression of different types of malignant tumors through various mechanisms." (PMID 34327141, 2021). "The lncRNA PCAT6 is a cancer/testis (CT) lncRNA that is normally silenced in healthy tissues except for the testes but is highly expressed in malignancies." (PMID 33634115, 2021). "Emerging evidence has shown that PCAT6, a newly discovered carcinogenic lncRNA, is abnormally elevated in various human malignant tumors." (PMID 34885209, 2021). "PCAT6 is an intergenic lncRNA that is located at chr1q32.1, and it is reported to have an oncogenic role in various human cancers." (PMID 34771549, 2021). "Numerous studies have reported that aberrant expression of PCAT6 in various types of cancer correlates with pathological features, such as tumor size, metastasis, degree of differentiation, TNM stage, and prognosis." (PMID 34247605, 2021). "Recently, the field of lncRNAs has attracted significant attention, and numerous studies have revealed that PCAT6 expression is up-regulated in various cancers, and that PCAT6 has the potential to become a new diagnostic biomarker and therapeutic target." (PMID 34247605, 2021). "Many investigations have demonstrated that the expression of PCAT6 is up-regulated in a variety of cancers and closely related to the occurrence and development of tumors." (PMID 34885209, 2021). "Furthermoer, PCAT6 expression level is also significantly higher in the blood samples of some cancer patients, including BC and LC." (PMID 34885209, 2021). "It has been well reported that lncRNA PCAT6 can act as an oncogene, which can drive the tumor progression in human cancers." (PMID 33552977, 2020). "It was revealed that PCAT6 was significantly upregulated in tumor tissues than in para-carcinoma tissues." (PMID 32908134, 2020). "After the PCAT6 knockdown, cancer cell proliferation was remarkably suppressed; also, PCAT6 knockdown enhanced CRC sensitivity to 5‐FU treatment." (PMID 30938104, 2019). "The activation of PCAT6 in LIHC co‐occurred with a number of genes in mitotic cell cycle and RNA processing, which were also the hallmark pathway of cancer." (PMID 30968586, 2019). "Herein, we assessed the specific functions of PCAT6 in CRC through measurement of cell viability, DNA synthesis ability, as well as the chemoresistance of cancer cells to 5‐FU‐based therapy in response to PCAT6 knockdown." (PMID 30938104, 2019). "PCAT6 was highly expressed in various cancers and may activate Wnt, PI3K/Akt/mTOR, and other pathways to regulate cell proliferation and migration; however, the mechanism of action of PCAT6 in HCC is unclear." (PMID 37373132, 2023). "In HCC, PCAT6 may inhibit cancer development by regulating the expression of hnRNPA2B1 through miR-326." (PMID 37373132, 2023). "There are many studies on the mechanism of PCAT6 in various types of malignant tumors." (PMID 36092924, 2022).
cancer (continued). "Summary of the mechanism studies of lncRNA PCAT6 in cancers." (PMID 34327141, 2021). "Finally, we validated PCAT6 expression in various cancers in lnCAR, an online analysis site based on Gene Expression Omnibus (GEO)." (PMID 34247605, 2021). "In summary, PCAT6 may be useful as a novel tumor predictor, and the critical role of PCAT6 in human cancers should be explored further." (PMID 34247605, 2021). "Overall, these findings suggest that PCAT6 may play an increasingly vital role in the clinical assessment of these malignant tumors." (PMID 34327141, 2021). "We also used NGDC to search and validate the expression of PCAT6 in various cancers." (PMID 34247605, 2021). "A total of eight cancers were analyzed and PCAT6 was highly expressed in all eight cancers." (PMID 34247605, 2021). "PCAT6 expression in various types of cancer was also validated in NGDC." (PMID 34247605, 2021). "LncRNA PCAT6 is highly expressed in multiple cancer types and its upregulation was significantly associated with patient prognosis and poorer clinical features, thereby suggesting that PCAT6 may be a novel prognostic factor in multiple cancer types." (PMID 34247605, 2021). "Furthermore, the aberrant expression of PCAT6 was also verified to be related to chemoresistance in cancers." (PMID 34885209, 2021). "Notably, the cancer nidus expressed a higher PCAT6 pattern, or a lower miR-326 tendency, as compared to the corresponding part of tissues (P < 0.05)." (PMID 33987473, 2020). "Several recent studies also presented the important role of PCAT6 in other cancers." (PMID 30968586, 2019). "Consequently, PCAT6 may be a new effective target for treatment in cancer patients undergoing clinical radiotherapy and chemotherapy resistance." (PMID 34885209, 2021). "To date, the precise molecular mechanism of PCAT6 in cancers remains unclear." (PMID 34327141, 2021). "This included the lncRNA/coding pair, PCAT6/KDM5B, and the coding/lncRNA pair, LHX1/LHX1-DT, which functions in malignant tumor cell growth." (PMID 37684517, 2023). "For example, lncRNA PCAT6 bound to RBM15 and IGF2BP3 in several cancer cell lines, which were determined by CLIP and eCLIP technology." (PMID 36032659, 2022). "Combining OS and disease-free survival (DFS) of these four types of cancer revealed a shorter OS and DFS in patients with PCAT6 overexpression." (PMID 34247605, 2021). "Therefore, PCAT6 may be a potential target for cancer diagnosis and treatment." (PMID 34885209, 2021). "We found that PCAT6 overexpression was significantly correlated with shorter OS and PFS in cancer patients." (PMID 34247605, 2021). "In addition, lncRNA SNHG6, LINC00520, PCAT6, KCNMB2-AS1, and DANCR, serving as ceRNAs, have been reported to be regulated in multiple cancers." (PMID 35909518, 2022). "Although PCAT6 has been reported to promote cell proliferation in a variety of cancers, the global gene expression profile regulated by PCAT6 has not been clarified." (PMID 35069911, 2022). "Several studies demonstrated that PCAT6 was overexpressed in several tumor tissues, such as GC, HCC, cervical cancer, NSCLC, lung cancer, and CRC, and this overexpression could facilitate the proliferation and metastasis of those cancers." (PMID 34771549, 2021). "Finally, NOL3 might be modulated by known cancer signaling proteins including Ras and HIF-1, and the lncRNA PCAT6, in CRC." (PMID 33193701, 2020).
tumor (29 papers, 2017 to 2025). "High levels of PCAT6 were remarkably associated with the tumor subtype, N classification, metastasis status, clinical stage, vital status, and a worse overall patient survival." (PMID 34327141, 2021). "Functionally, increased PCAT6 levels were positively associated with tumor size, TNM stage, lymph node metastasis, and poor OS." (PMID 34327141, 2021). "Then, via establishing CCA xenograft mouse model, we found loss of PCAT6 obviously triggered the immune response and reduced the in vivo tumor growth." (PMID 33552977, 2020). "Then, to confirm the expression of PCAT6 in tumor-associated immune cells, immunofluorescence analysis was carried out and we found that PCAT6 expression in CD11b+ cells within tumor tissues was greatly higher." (PMID 33552977, 2020). "Subsequently, many studies have demonstrated that lncRNA PCAT6 expression is elevated in various tumors and that this may be linked to tumor progression." (PMID 36787056, 2023). "Moreover, this study showed that PCAT6 is associated with autophagy and that PCAT6 probably increases tumor malignancy via autophagy pathways." (PMID 34692467, 2021). "Colony formation assay, MTT assay, cell cycle analysis, EdU assay, Transwell migration and invasion assays, wound healing assay, and in vivo experiments were carried out to investigate the function of prostate cancer‐associated transcript 6 (PCAT6) in bone metastasis and tumor growth of PCa." (PMID 34185427, 2021). "Loss of PCAT6 reduced in vivo tumor growth via activating immune responses." (PMID 33552977, 2020). "The obtained results confirmed that ASO-mediated knockdown of PCAT6 reduces bone metastasis and tumor growth in vivo." (PMID 41157107, 2025). "Focusing on lncRNAs, PCAT6 has been identified as a key promoter of prostate cancer tumor growth, invasion, and metastasis." (PMID 38249783, 2024). "In vivo limiting dilution assays revealed that the loss of PCAT6 dramatically reduced tumor incidence, and reduced CD44+ breast CSCs, c‐MYC, and Ki67 were detected in PCAT6 knockdown cell‐formed xenografts compared with control xenografts." (PMID 38626369, 2024). "Conclusively, the hypoxic lncRNA PCAT6 plays a crucial role in BC cell stemness maintenance and tumor progression." (PMID 38626369, 2024). "Decreased PCAT6 levels can stimulate the immune response and inhibit tumor growth, while increased PCAT6 leads to the polarization of macrophages towards the M2 type, which promotes tumor growth." (PMID 39290697, 2024). "Conversely, ectopic PCAT6 overexpression markedly increased tumor incidence and CD44+ breast CSCs, c‐Myc, and Ki67 expression in xenografts." (PMID 38626369, 2024). "Compared with that in normal tissues, the expression of PCAT6 in tumor tissues is abnormally elevated." (PMID 38606479, 2024). "For a comprehensive understanding of PCAT6's role in tumor progression, transcriptomic profiling of PCAT6 WT (Hs578T/shNC) and PCAT6 deficient cells (Hs578T/shPCAT6) under hypoxia was performed using RNA‐seq." (PMID 38626369, 2024). "Functional assays in Lang C’s studies confirmed that PCAT6 knockdown also significantly inhibited PCa cell invasion, migration, and proliferation in vitro, bone metastasis, and tumor growth in vivo; however, the mechanism of action of PCAT6 in HCC is unclear." (PMID 37373132, 2023). "To verify this finding, we used RT-qPCR to detect lncRNA PCAT6 expression in 25 LUAD tumor and adjacent normal tissue samples." (PMID 36787056, 2023). "PCAT6 knockdown in vitro inhibited PCa cell migration, invasion, and proliferation, and counteracted tumour growth and bone metastasis development in vivo." (PMID 37143733, 2023). "And differential expression of PCAT6 was observed in the database which containing 182 ESCC tumor tissues and 13 normal tissues were included." (PMID 35069911, 2022).
tumor (continued). "In conclusion, our study reveals that lncRNA PCAT6 functioned as a tumor promoter in the progression of ESCC by regulating the expression of genes related to cell proliferation and migration." (PMID 35069911, 2022). "PCAT6 is abnormally overexpressed in PCa, and promotes tumor cell proliferation as well as invasion in an androgen-independent way." (PMID 34277403, 2021). "In this review, we summarize the biological characteristics of PCAT6 in a variety of human malignancies and describe the biological mechanisms by which PCAT6 can facilitate tumor progression." (PMID 34885209, 2021). "In NSCLC PCAT6 absorbs miR-330-5p and promotes cell proliferation, migration, invasion in vitro, and tumor growth in vivo." (PMID 34885209, 2021). "Interference of PCAT6 or the accumulation of miR-139-3p impedes tumor growth, induces apoptosis and promotes the EMT process in vivo." (PMID 34885209, 2021). "In Osa, overexpression of PCAT6 enhances cell proliferation, migration, and invasion in vitro, and tumor growth in vivo, while depression of MDM2 proto-oncogene (MDM2) exerts an opposite influence." (PMID 34885209, 2021). "The high expression of PCAT6 was also correlated with aggressive tumor phenotype, affecting clinical stage and lymph node metastasis." (PMID 34327141, 2021). "PCAT6 promotes tumorigenesis through the PCAT6/miRNA/mRNA axis, which in turn affects different biological behaviors of tumor cells." (PMID 34885209, 2021). "Functional experiments indicated that PCAT6 knockdown significantly inhibited PCa cell migration, invasion, and proliferation in vitro, as well as BM and tumor growth in vivo." (PMID 34185427, 2021). "Previous studies showed that PCAT6 mainly acted as an endogenous competitive RNA by sponging miRNAs to enhance tumor progression." (PMID 34185427, 2021). "Correlation analyses showed that PCAT6 expression is related to tumor size, differentiation, TNM stage, lymph node metastasis status, and distant metastasis status, but not gender or age." (PMID 34327141, 2021). "PCAT6 expression was also negatively correlated with tumor size, TNM stage, metastasis status, and GC prognosis." (PMID 34327141, 2021). "To explore the biological function of PCAT6 in PCa, we performed gene set enrichment analysis (GSEA) based on TCGA data, and the results suggested that PCAT6 was related to tumor metastasis." (PMID 34185427, 2021). "To further investigate the biological function of IGF1R in PCAT6‐induced BM and tumor growth, we overexpressed IGF1R in PCAT6‐silenced PC‐3 and C4‐2B cells." (PMID 34185427, 2021). "The results of animal experiments uncovered that depletion of PCAT6 inhibited tumor growth by activating the T cell response in vivo, which was mainly manifested by the increase of CD3+ T cells and IFN-γ-producing CD4+ T and CD8+ T cells." (PMID 34885209, 2021). "Until now, PCAT6 has been found to sponge various miRNAs to activate the signaling pathways, which further affects tumor cell proliferation, migration, invasion, cycle, apoptosis, radioresistance, and chemoresistance." (PMID 34885209, 2021). "Functional experiments found that PCAT6 knockdown significantly inhibited PCa cell invasion, migration, and proliferation in vitro, as well as bone metastasis and tumor growth in vivo." (PMID 34185427, 2021). "In CC, PCAT6 promotes cell proliferation and metastasis in vitro, and tumor growth in vivo through the miR-543/ZEB1 axis." (PMID 34885209, 2021). "In vivo assays were also established to explore the impact of PCAT6 on tumor growth and microangiogenesis." (PMID 32908134, 2020). "According to clinicopathological feature analysis using chi‐square test, higher PCAT6 expression was correlated with larger tumor size (P = 0.014), advanced TNM stages (P = 0.007), and lymph node metastasis (P = 0.038)." (PMID 30938104, 2019). "↓ brain metastasis and tumor growth in vivo via PCAT6/IGF2BP2/IGF1R pathway." (PMID 41157107, 2025).
tumor (continued). "Furthermore, PCAT6 knockdown decreased xenograft tumor growth in mice, and tumor growth of xenografts derived from shPCAT6 spheres was severely suppressed by doxorubicin treatment." (PMID 38626369, 2024). "Cell lines and xenograft mouse models are used to examine the impact of PCAT6 on tumor metastasis." (PMID 38606479, 2024). "In addition, NSCLC cell-secreted exosomal lncRNA PCAT6 has been found to induce M2 polarization, favoring tumor growth by promoting tumor cell invasion and migration." (PMID 36612282, 2022). "LncRNA PCAT6 has been identified as a tumor promoter in multiple cancers." (PMID 35069911, 2022). "Prostate cancer associated transcript-6 (PCAT6), which has been reported in previous studies, was found upregulated in tumor tissues and could promote the tumor progression in multiple cancer types 20-23." (PMID 35069911, 2022). "In the current study, we found that PCAT6 was significantly upregulated in ESCC tumor tissues, suggesting that PCAT6 might function as a tumor promoter in the progression of ESCC." (PMID 35069911, 2022). "From the results, we observed that PCAT6 was significantly elevated in ESCC tumor tissues." (PMID 35069911, 2022). "Six studies reported the correlation between PCAT6 overexpression and tumor size." (PMID 34247605, 2021). "Further functional predictions suggest that PCAT6 is correlated with tumor prognosis, and that PCAT6 may be useful as a new tumor-specific marker." (PMID 34247605, 2021). "Meanwhile, PCAT6 has been shown to promote tumor growth and metastasis in xenograft mouse models." (PMID 34885209, 2021). "In addition, more studies have found that the accumulation of PCAT6 is closely related to the prognosis of various tumor patients." (PMID 34885209, 2021). "Moreover, the results of a subcutaneous xenotransplanted PA mice model have demonstrated that PCAT6 knockdown and miR-139-3p overexpression can induce the increase of the E-cadherin protein level and the decrease of the N-cadherin level in tumor tissues." (PMID 34885209, 2021). "Our study uncovers a novel molecular mechanism by which the m6A‐induced PCAT6/IGF2BP2/IGF1R axis promotes PCa bone metastasis and tumor growth, suggesting that PCAT6 may serve as a promising prognostic marker and therapeutic target against bone‐metastatic PCa." (PMID 34185427, 2021). "According to these data, PCAT6 is expected to be a promising target for tumor therapy." (PMID 34327141, 2021). "Then, we investigated the role of PCAT6 in tumor growth and metastasis in vivo." (PMID 34277403, 2021). "Furthermore, PCAT6 overexpression promotes tumor cell proliferation, migration, invasion, chemoresistance, and radioresistance." (PMID 34885209, 2021). "The current results demonstrate that PCAT6 acted as a tumor activator in PCa progression by sponging miR-326 and increasing Hnrnpa2b1 expression and that the PCAT6/miR-326/Hnrnpa2b1 signaling might be a new therapeutic target for PCa." (PMID 34277403, 2021). "Therefore, PCAT6 plays a vital tumor-promoting role, partially dependent on regulation of the miR-143-3p/ZEB1 axis." (PMID 34327141, 2021). "In this work, we observed PCAT6 was increased in CCA tissues and tumor-associated macrophages." (PMID 33552977, 2020). "In this section, the in vivo assays were conducted to verify the function of PCAT6 on tumor growth." (PMID 32908134, 2020). "Thus, lncRNA PCAT6 has potential to be a valid tumor marker for LUAD." (PMID 36787056, 2023). "Furthermore, PCAT6 knockdown inhibited BM and tumor growth of PCa cells." (PMID 34185427, 2021). "Therefore, PCAT6 may regulate tumor biological behaviors through different molecular mechanisms, but research on autophagy pathways is still lacking." (PMID 34692467, 2021). "PCAT6 stabilizes the mRNA of IGF1R through its interaction with IGF2BP2 and IGF1R, activating pathways that encourage tumor growth and metastasis." (PMID 38249783, 2024).